AHR (aryl hydrocarbon receptor)
Diseases named in the same sentence as AHR in open-access papers (continued):
Sharing a sentence is not in itself a finding about the gene and the disease.
cancer (continued). "Metabolites such as indole-3-acetic acid (IAA) can activate the aryl hydrocarbon receptor (AhR), leading to differential expression of cytokines and changes in immune cell composition, thereby providing support for the regulation of anti-cancer immune checkpoints." (PMID 41158775, 2025). "Initially identified as a target gene of AHR, we now know that PARP7 interacts with many other transcription factors, which regulate various physiological processes and are implicated in cancer, making PARP7 an attractive target for the development of novel therapeutics." (PMID 40128585, 2025). "In contrast, bilirubin and biliverdin, as endogenous agonists of the AhR, may reduce the proliferation of cancer cells due to the AhR stimulation." (PMID 40291905, 2025). "The AhR ligands function as selective AhR modulators (SAhRMs), exhibiting agonistic or antagonistic effects on several hallmarks of cancer, e.g. evading growth suppressors, sustained proliferative signals, resistance to cell death, inflammation and activation of invasion and metastasis." (PMID 40646277, 2025). "We identified effective small-molecule AhR antagonists for cancer immunotherapy." (PMID 41155994, 2025). "Moreover, it is known that AhR modulates cell proliferation and apoptosis among various cell types such as cancer and immune cells; our results revealed that Ahr silencing does not affect cell viability, nor the induction of apoptosis." (PMID 39791758, 2025). "This approach allowed us to focus specifically on AHR-related changes in cancer cells." (PMID 40248203, 2025). "Recent reports show that AhR plays a critical role in cancer development and maintenance." (PMID 40141386, 2025). "Additionally, using unbiased clustering, we analyzed the AhR expression patterns, identified the characteristics of three common clusters across cancer types, and examined their distribution in five solid tumors." (PMID 38680496, 2024). "Another review article also highlighted that formate-producing F. nucleatum stimulates the aryl hydrocarbon receptor (AhR) signaling pathway, thereby promoting cell migration and eliciting cancer stem cell (CSC) traits, high metastatic activity and active Wnt signaling." (PMID 38667331, 2024). "In addition to regulating AhR and the xenobiotic response, AIP has been linked to various aspects of cancer and immunity that will be the focus of this review article." (PMID 38479600, 2024). "AHR deletion in various cancer types influences cell proliferation, invasion, and differentiation." (PMID 39336758, 2024). "Thus, inhibiting AHR activity represents an exciting therapeutic strategy to target multiple cancer dependencies by blocking kynurenine signaling downstream of IDO1 and TDO2." (PMID 39450255, 2024). "Presently, many studies have shown that AhR is involved in the process of cancer metabolic reprogramming by binding with different ligands and that novel interventions targeting AhR may have notable clinical value." (PMID 38434684, 2024). "In a culture of human A549 cancer cells exposed to lead, a significant increase in NF-κB and aryl hydrocarbon receptor (AhR) transcription factor levels and their target gene products was described, confirming the involvement of corresponding signaling pathways in lead-induced inflammation." (PMID 39056765, 2024). "This activation of AhR facilitates cancer cell movement and inhibits the immune response." (PMID 38691253, 2024). "However, it has also been observed that certain AhR agonists or activators can suppress various types of cancer." (PMID 38792249, 2024). "Increased exposure in African American men may amplify AHR activity, leading to more aggressive cancer." (PMID 39600743, 2024). "These up-and-coming trials are promising and could represent the first AhR modulators to be clinically approved in patients for cancer therapy." (PMID 38807762, 2024). "AhR is ubiquitously expressed and dysregulated in a wide range of cancer types." (PMID 38807762, 2024).
cancer (continued). "In addition, AHR and its ligands (agonists or antagonists) are expected to become new targets for blocking cancer." (PMID 38497715, 2024). "Although AhR expression differs among cancer types, AhR is generally expressed in most tumors." (PMID 38680496, 2024). "Yet, the long-term impact of sustained AhR activation on cancer progression remains uncertain." (PMID 38653790, 2024). "TCDD-activated AhR upregulates MMP9 expression activity in a variety of malignant tumors." (PMID 38434684, 2024). "ITE interacts with AHR and suppresses Oct4 expression, directing cancer stemness and growth." (PMID 38612627, 2024). "Additionally, the oncogenic metabolite Kyn activates the Aryl Carbon Receptor (AhR) pathway, which serves as a pro-tumoral factor, influencing the invasive properties of cancer cells." (PMID 38653790, 2024). "The aryl hydrocarbon receptor (AhR) is a cytoplasmic and environmental receptor that responds to both exogenous and endogenous ligands to impart a broad range of functions and thereby significantly impact cancer progression." (PMID 38339226, 2024). "AhR is an important cytosolic, ligand-dependent transcription factor, and evidence suggests its role in the initiation, promotion, progression, invasion, and metastasis of cancer cells." (PMID 38610738, 2024). "AhR has been shown to influence expression of stem-related genes in multiple cancer types." (PMID 38339226, 2024). "Our findings may elucidate the mechanisms underlying AhR-mediated pathways in cancer and immune cells in the TME across different cancer types." (PMID 38680496, 2024). "Cluster 1 exhibited high AhR expression in cancer cell nucleus, while cluster 3 showed the lowest." (PMID 38680496, 2024). "The question remains unanswered as to whether AhR is a target for preventing carcinogenesis, particularly for cancers originating from barrier organs." (PMID 38518996, 2024). "By demonstrating different expression patterns of AhR in cancer cells and immune cells, our findings are anticipated to provide a fundamental basis for both biological and immunological research on drugs targeting AhR." (PMID 38680496, 2024). "Regarding its association with molecular targets relevant to cancer prevention, quercetin aglycone has been shown to interact with certain receptors, in particular the aryl hydrocarbon receptor, which is involved in the development of cancers induced by certain chemicals." (PMID 39795061, 2024). "The aryl hydrocarbon receptor (AHR) serves as a ligand-activated transcription factor crucial for regulating fundamental cellular and molecular processes, such as xenobiotic metabolism, immune responses, and cancer development." (PMID 38612627, 2024). "Additionally, low-dose BPA exposure activates AHR in breast cancer cells, increasing their aggressive cancer cell phenotype." (PMID 38612627, 2024). "Tailoring AHR-targeted therapies to specific stages of cancer progression could enhance their efficacy and reduce unintended effects on normal immune function." (PMID 39690159, 2024). "Notably, this includes synthesizing novel AhR modulators as well as repurposing existing agents for the treatment of cancer patients." (PMID 38807762, 2024). "Furthermore, AhR influences the occurrence and development of cancer by regulating microRNA and small non-coding RNAs." (PMID 38518996, 2024). "The bacterial indole pathway in tryptophan catabolism may also play a role in activating AhR to induce cancer." (PMID 38448800, 2024). "This section presents only an overview of the AhR functions related to cancer." (PMID 39339278, 2024). "These interactions have been demonstrated to drive cancer progression and metastasis through mechanisms including the activation of AhR signaling by products of tryptophan metabolism from Lactobacillus species and the production of formate from Fusobacterium nucleatum." (PMID 39766077, 2024). "UCHL3 enhances cancer cell stemness through intermediary receptor molecules like AhR." (PMID 38965582, 2024).
cancer (continued). "We also examined the preclinical efficacy data of AhR agonists and antagonists on carcinogenesis to determine whether AhR modulation can be a viable option for cancer chemoprevention." (PMID 38518996, 2024). "Furthermore, T cells and macrophages in the stromal environment expressed AhR, consistent with the results obtained for other cancer types." (PMID 38680496, 2024). "For applications in cancer prevention, future studies may investigate the targeted delivery of AhR agonists or antagonists to specific immune cells." (PMID 38518996, 2024). "Despite these efforts, the role of AhR in different cancer types at different stages remains unclear." (PMID 38680496, 2024). "AhR functions as a complex metabolic regulator and transcription factor in most cancer cells." (PMID 38434684, 2024). "However, the AhR and its interactions with other signaling pathways, including Nrf2, and ERs make it a potentially significant target for cancer treatment and chemoprevention, especially concerning naturally occurring phytochemicals and their derivatives." (PMID 39339278, 2024). "AhR-mediated mechanisms have opened new horizons for an effective cancer therapy." (PMID 37830596, 2023). "Nuclear fractions of TCDD-treated cancer cells showed a reduced level of SUMOylated AhR." (PMID 37830596, 2023). "Therefore, further studies are required to develop a better comprehension of the many-sided and “diametrically opposed” roles of AhR in the regulation of carcinogenesis and metastatic spread of cancer cells to the secondary organs." (PMID 37830596, 2023). "AhR’s role in drug resistance, like its role in cancer, is variable." (PMID 36831661, 2023). "Our results suggested that there could be different self-regulation mechanisms or different biological interactions between KYN and AhR in normal and cancer cells within the skin." (PMID 37245164, 2023). "Based on these results, one may hypothesise that IDO and AhR inhibitors, which are currently being tested in cancer, could benefit individuals with ASD although, their side effects may restrict their use." (PMID 38071324, 2023). "While the complexity of AHR signaling may appear daunting for interventions such as cancer therapy, the AHR shares such complexity with many other drug targets." (PMID 37696456, 2023). "Additionally, this AhR activation promotes cancer cell proliferation and migration in a cell-autonomous way." (PMID 37999261, 2023). "Several IDO1 and AhR inhibitors are now in clinical trials as potential cancer therapies." (PMID 37744363, 2023). "Kyn concentration may range from 0.1 to 0.5 μM in normal blood but increases to up to 1 μM in individuals with cancer, which has pathophysiological effects by activating AhR of target cells." (PMID 37919525, 2023). "This ROS production alters some cell function, such as cell migration, apoptosis, inflammation, and the epithelial-mesenchymal transition, which is required for cancer initiation, by disrupting the balance of cellular ROS generated by the AhR-Nrf2 gene battery." (PMID 37596694, 2023). "It was shown that Isofistularin-3 demethylated AhR and induced apoptosis in cancer cells." (PMID 37830596, 2023). "Modulation of CYP enzyme activity may hence contribute to the complex biology of AHR activity in cancer and beyond." (PMID 37696456, 2023). "It is well established that AhR plays central roles in both innate and adaptive immune responses with vigorous modulatory effects, which makes AhR an attractive target for the development of cancer immunotherapies." (PMID 37241719, 2023). "How AhR regulates apoptosis in TRAIL-treated cancer cells is an exciting area of research." (PMID 37830596, 2023).
cancer (continued). "Intriguingly, cancer cells appear to utilize this AhR-mediated pathway." (PMID 37696458, 2023). "Further, unrealized therapeutic opportunities may exist to exploit the activation of AhR in cancer types that feature the elevated activity of pathways controlled by the receptor." (PMID 37106727, 2023). "Thus, in this review, we shed light on the modulation of AhR signaling in cancer immunotherapy as a potential therapeutic strategy." (PMID 37241719, 2023). "In this respect, identifying the cancer types that respond positively to the activation of AhR, identifying overexpressed or silenced factors that modulate the response of AhR, and identifying the stage(s) of tumorigenesis when the activation of AhR drives the inhibition of growth is paramount." (PMID 37106727, 2023). "A research article about cancer stem cells (CSCs) from human choriocarcinoma cell line JEG-3 revealed that the activation of AhR by TCDD induces the expression of β-catenin and its nuclear translocation and initiates the expression of β-catenin targets: cyclin D1 and c-Myc." (PMID 37232717, 2023). "Conversely, the AhR complex inhibits ESR signaling in the presence of estrogen that would otherwise normally transcribe genes such as FOS, CTSD, HSP27, and TFF1, which are over-expressed and/or mutated in various cancers." (PMID 37027342, 2023). "Although it limited the progression of cancer on the one hand, which may be related to EBVaGC low lymphatic metastasis and good prognosis, it may also increase the difficulty of treatment with AHR as the target on the other hand." (PMID 36829212, 2023). "Furthermore, evidence indicates that the activation of the aryl hydrocarbon receptor (AhR) can promote cancer cell metastasis." (PMID 38303976, 2023). "The SNP frequencies for AHR (rs2066853) and SLC45A2 (rs26722) gene minor variants (MT) were found to be less than 1.00%; similar findings were published by De Sousa and colleagues related to cancer patients." (PMID 37763073, 2023). "Furthermore, AhR and epigenome dynamics have shown previously unprecedented complexity during multiple stages of cancer progression." (PMID 37830596, 2023). "Notably, increasing evidences suggest that the binding of tryptophan derivatives with AhR play a role in the pathogenesis or treatment of many skin diseases, including inflammatory diseases, skin pigmentation diseases, and cancer." (PMID 38318507, 2023). "For instance, cancers that feature elevated Wnt signaling or acquire resistance to existing Wnt pathway inhibitors could be candidates for AhR-targeted therapeutics." (PMID 37106727, 2023). "However, to exploit the AHR for cancer therapy a comprehensive understanding of its complex activation and diverse biological outcomes is necessary and we expect the described mechanisms to also apply to cancer." (PMID 37696456, 2023). "Design of AhR targeting PROTACS is also an exciting strategy to prevent AhR-overexpressing cancers." (PMID 37830596, 2023). "Therefore, activation of AhR is related to the pathogenesis of several diseases, such as cancer, cardiovascular disease, inflammatory diseases, atherosclerosis, and neurodegenerative diseases." (PMID 37048160, 2023). "One possible explanation for this observation is that lower AHR expression in PBMCs might have a different AHR background in cancer tissue." (PMID 37760608, 2023). "Accordingly, without activation, AhR suppressed the expression of the cancer-associated miR-96, whereas chronic cigarette smoke markedly increased its level by a mechanism independent of classic AhR activation by ligands." (PMID 37696458, 2023).
cancer (continued). "Overall, these findings indicated that HDAC inhibitors impaired the activity of HDAC to impair invasive properties of cancer cells by facilitating an increase in the formation of AhR/HDAC complexes for the inhibition of HDAC activities and stability of histone acetylation patterns." (PMID 37830596, 2023). "The role of AhR in metastasis and cancer stemness seems to be rather complex and may involve various signaling pathways and cell types." (PMID 37696458, 2023). "The data suggested that the TDO2–kynurenine–AHR interaction was responsible for the hepatic metastases of colonic cancer, probably due to inducing PD-L1 and its ability to simultaneously inhibit immune surveillance and promote cancer cell stemness." (PMID 37296860, 2023). "Overall, the functional analysis indicated that esketamine suppressed ERCC6L, AHR and KIF2C may be the underlying mechanisms for its anti-cancer effects, although further study is needed." (PMID 37968758, 2023). "Biseugenol activated Calpain-10-mediated cleavage of AhR in the cancer cells." (PMID 37830596, 2023). "AHR glycogenolysis occurs in patients with chemoresistant cancer." (PMID 38099490, 2023). "While too extensive to completely review here, different tryptophan-derived ligands such as FICZ, 2-(10-H-indole-3-carbonyl) thiazole-4-carboxylic acid methyl ester (ITE), and indole-3-carbinol (I3C) have been explored as experimental and therapeutic AhR agonists for cancer and immune diseases." (PMID 37106727, 2023). "Various clinically approved drugs including omeprazole, 4-hydroxytamoxifen, flutamide, leflunomide, and nimodipine, activate the AHR without increasing cancer risk." (PMID 37696456, 2023). "Kynurenine-mediated activation of AhR leads to the immunological escape of cancer cells." (PMID 37830596, 2023). "Thus, activated AhR is present in MEPs in individuals with cancer, which provides new insights into MEP fate decisions." (PMID 37919525, 2023). "This in turn should contribute to unravel the mechanism(s) of action how AhR activation may control acute and chronic inflammatory conditions in infection, cancer, or immune-mediated diseases as shown by many authors." (PMID 37287978, 2023). "Currently, controversy exists about AhR's role in cancer and cancer cells." (PMID 37056388, 2023). "Moreover, the aryl hydrocarbon receptor (AhR) pathway was also found to be active in certain cancer cells together with the Th cells." (PMID 36982245, 2023). "By activating AhR signaling, Kyn and I3P were found to enhance cancer cell migration in vitro." (PMID 37196768, 2023). "AHR has been reported to promote cancer stem cell (CSC) reprogramming." (PMID 38099490, 2023). "There was an evident increase in the expression of AhR in Isofistularin-3-treated cancer cells." (PMID 37830596, 2023). "Together, these results implied that sulfenylated AHR–regulated glycogenolysis might contribute to chemoresistance in patients with cancer." (PMID 38099490, 2023). "Upon ligand binding, AHR translocates into the nucleus and regulates target gene transcription, which is critical for biological processes, including normal development, immunity, and cancer development." (PMID 37655051, 2023). "Furthermore, the combination of AHR and cytokine signaling has been demonstrated to enhance growth factor expression in carcinoma cell lines." (PMID 37755265, 2023). "Moreover, overexpression of AHR, which occurs in mice supplemented with IPA, masks the benefits of IPA, and many studies have reported that AHR overexpression can lead to malignant phenotypes such as cancer." (PMID 36615808, 2022). "AHR enables cells to adapt to changing conditions by sensing compounds from the environment, diet, microbiome, and cellular metabolism, which plays an important role in development of and immunity to cancer." (PMID 36358336, 2022).